LEP (leptin)
Diseases named in the same sentence as LEP in open-access papers (continued):
Sharing a sentence is not in itself a finding about the gene and the disease.
depression (continued). "In terms of depression, leptin could modulate the levels of neurotransmitters, neurotrophic factors and reverse the dysfunction in the hypothalamic-pituitary-adrenal axis (HPA)." (PMID 31130833, 2019). "In the contrast, some studies demonstrated that leptin have antidepressant and anxiolytic effects and might be a potential therapeutic target for depression." (PMID 31354416, 2019). "Our results need to be confirmed by more comprehensive studies with detailed demographical and psychological data with clinical symptoms, metabolic factors and specific medication information to decipher the roles of leptin in the pathophysiology of depression and brain abnormalities." (PMID 31354416, 2019). "Studies have shown that leptin levels are higher in depression patients than in control groups." (PMID 31130833, 2019). "However, there is also research demonstrating that patients with major depression disorder have higher leptin levels." (PMID 31130833, 2019). "Recent studies have shown that dysregulation of leptin may be related to mechanisms of psychopathology, including various emotional changes, such as anxiety, depression, sleep disorders, and suicide." (PMID 31500186, 2019). "These functions of leptin reflect its potential to treat depression." (PMID 31130833, 2019). "Indeed, this previous study showed that animals exposed to stress-induced depression present low plasma levels of leptin, while leptin treatment restores these parameters." (PMID 30949073, 2019). "Decreased nocturnal leptin levels owing to night eating can interfere with sleep or promote appetite, which in turn leads to a vicious cycle of night eating, impaired sleep, and depressive disorders." (PMID 31805668, 2019). "We suggest that decrease in BDNF by the activated NLRP3 inflammasomes in astrocytes is the key pathological event of the depressive-like behaviors induced by SD, while the combined treatment with fluoxetine and leptin improves therapeutic outcome for the depression induced by SD." (PMID 30666218, 2018). "The gender ratio of depressive and healthy subjects is a key factor that may address studies examining the role of leptin in depression." (PMID 30367065, 2018). "A number of clinical studies have investigated the link between leptin and depression." (PMID 30367065, 2018). "Leptin may influence these mechanisms and consequently constitute a possible target for novel therapeutic approaches to the treatment of depression." (PMID 30367065, 2018). "Several basic studies suggest that leptin has antidepressant effects and might be a potential therapeutic target for depression." (PMID 30367065, 2018). "Moreover, some studies focusing on leptin and depression showed sex differences in the relationship." (PMID 29176959, 2017). "However, leptin is also involved in the stress response and stress-related disorders, including depression and anxiety." (PMID 28442988, 2017). "The leptin levels are decreased in depression, and the administration of leptin may improve depressive symptoms." (PMID 28226002, 2017). "Prior literature has also suggested a relationship between leptin and depression." (PMID 29176959, 2017). "One recent study showed that reduced leptin concentrations could be a potential predictor of reduced depression symptoms in obese adolescents, and the results were stronger in girls than in boys." (PMID 29176959, 2017). "However, depression patients had the almost equal serum leptin and LepRb concentration (3.5 ng/mL and 2.3 ng/mL, resp)." (PMID 28316984, 2017). "Since the role of this adipokine on anxiety and depression has been scarcely explored, further investigation is needed to determine the possible role of leptin resistance or hyperleptinemia and increased plasma levels of resistin in the increased anxiety-like behavior observed in our MS model." (PMID 28463967, 2017).
depression (continued). "In addition, leptin is involved in cytokine-induced depression, as ICV leptin administration induces depression-like behavior, while leptin antagonism attenuates particular components of this behavioral response." (PMID 29213271, 2017). "Negative associations of leptin and depression as well as anxiety have been reported outside the context of AN." (PMID 28030575, 2016). "Leptin effects on memory and cognition might be confounded by the coexistence of neuropsychiatric disorders such as depression, schizophrenia and substance-related disorders." (PMID 27797980, 2016). "In contrast, negative associations of leptin and subjective ratings of depression, anxiety, and stress were observed in LSS patients." (PMID 28030575, 2016). "Leptin and LepRb were also found to play a role in the pathogenesis of depressive disorder." (PMID 27739518, 2016). "Some of the changes in leptin may be mediated to some degree by decrease in BDNF which are observed in depression." (PMID 26231223, 2015). "It is known that leptin plays a role in depression- and anxiety- related behaviors." (PMID 26382238, 2015). "However, the evidence concerning the interrelationship among leptin, adiponectin, ghrelin and depression is still limited and controversial." (PMID 26183327, 2015). "Leptin is an endocrine signaling molecule that has an established role in regulating energy use and nutritional intake, but it appears to also play a role in the pathophysiology of depression and anxiety." (PMID 26303856, 2015). "Although these findings seem to support a reduction of leptin levels in animal models of depression, the current knowledge on the role of leptin signaling in human depression remains unclear." (PMID 25386150, 2014). "Thirdly, elevated serum leptin in depression might in turn further promote corticotropin-releasing hormone (CRH) release, as shown in animals and, hence, contribute to HPA system hyperactivity seen in depression." (PMID 25061971, 2014). "Given important roles of leptin and ghrelin in the regulation of appetite and weight, depressive status as well as medication for depression may also influence the levels of these hormones." (PMID 25079305, 2014). "Previous investigations have reported a decrease in depressive manifestations after a weight loss treatment, however, this study specifically demonstrates a relationship of the decrease in CRP and leptin with the reduction in self-perceived depression in subjects suffering MetS." (PMID 24762259, 2014). "Our aim was to determine whether there was a relationship between inflammatory markers (leptin) and post-stroke depression (PSD)." (PMID 25061971, 2014). "Neurotrophic actions of leptin may be another mechanism explaining the relationship with depressive disorders." (PMID 25079305, 2014). "Epidemiological findings on leptin levels and depression are conflicting." (PMID 24109426, 2013). "Leptin has antidepressant effects when administered into the hippocampus, an area mediating cognitive impairments of depression whereas genetic deletion of hippocampal LepRb results in a depression-like phenotype." (PMID 24109426, 2013). "Finally, both fat% and leptin plasma levels in the current study correlated negatively at follow-up with psychological measurements such as anxiety, obsessions, depression (as measured with CPRS-S-A), and various subscales of EDI-2." (PMID 24205172, 2013). "However, other reports show that plasma leptin levels are increased in women with depressive disorder and that leptin levels are either increased or not changed by antidepressant treatment." (PMID 24109426, 2013). "Indeed, exposure of rodents to stress paradigms, which induce various behavioural deficits resembling certain aspects of human depression, results in significant decreases in the circulating levels of leptin [43•]." (PMID 18024215, 2007).
depression (continued). "In line with this, our results posit that stress-inducing anxiety and depression observed in pregnant women could be due to the increased circulating levels of both leptin and resistin, in addition to other immune biomarkers shown to be increased in pregnant subjects with major depression." (PMID 40565847, 2025). "In addition, physiological factors (hormones such as GLP-1, PYY, and leptin), psychiatric conditions (depression, anxiety), and behavioral aspects (maladaptive eating behaviors, binge eating, and FA) may also contribute to suboptimal WL after BS." (PMID 40647219, 2025). "Diminished leptin signaling may, therefore, contribute to both metabolic and affective symptoms of atypical depression, a second metabolic signal changing general neurocognitive factors (reward and motivation) in parallel with its role on appetite-related processes." (PMID 40991698, 2025). "Interestingly, this may also be related to leptin, as it has been suggested that leptin insufficiency and/or resistance may contribute to the development of depression." (PMID 38668349, 2024). "Abdominal obesity may affect plasma levels of adiponectin, leptin, cortisol, resistin, insulin, and inflammatory cytokines, such as tumour necrosis factor-α and interleukin-1β, which can enhance neuroinflammation and contribute to depression." (PMID 39487412, 2024). "Overall, our findings suggest that repeated infusions of ketamine may produce a positive and longer-term effect on BMD, and leptin and OC may be the potential biomarkers of antidepressant response to ketamine in female and male patients with depression, respectively." (PMID 38287453, 2024). "However, the pharmacology and pathophysiology of leptin signaling defect in causing depression is not well understood." (PMID 38029397, 2024). "An improved leptin sensitivity may contribute to a reduction in depression." (PMID 38098007, 2023). "Reduced leptin concentration and increased BDNF levels in physically fit adolescents are related to lower levels of depression and have also been positively associated with memory function, which may be related to lower depressive symptoms and cognition, positively influencing AP." (PMID 36264339, 2023). "Chronic stress reduces leptin levels and offers hypotheses: decreased leptin production may contribute to depression-like manifestations, the hippocampus may mediate antidepressant-like effects of leptin, and enhanced brain leptin signaling might aid in the treatment of depressive disorders." (PMID 37938494, 2023). "Similarly, high serum levels of leptin are observed in patients with major depression." (PMID 36225193, 2022). "It is speculated that the lack of a relationship between being overweight and depression may be due to leptin absence or neuropeptide Y, which are associated with depressive symptoms." (PMID 36354390, 2022). "In addition, raising the level of inflammatory cytokines such as interleukein 6, C-reactive protein, and leptin resistance may also be involved with depression." (PMID 35458097, 2022). "However, whether leptin is a factor in determining adolescent vulnerability to chronic stress exposure and depression symptoms like social anhedonia is unknown." (PMID 36138127, 2022). "Therefore, it is speculated that low leptin and amino acid levels owing to poor nutrition may be contributing factors to depression development." (PMID 36354390, 2022). "Thus, dysregulation of BDNF presumably could lead to resistance to leptin, contributing to the pathogenesis of depression and Alzheimer’s disease." (PMID 33106599, 2021). "Indeed, obese depression patients display high levels of leptin in plasma." (PMID 32408603, 2020). "However, the relationship between circulating leptin levels and depression is under debate." (PMID 33066277, 2020).
depression (continued). "In addition, a positive association between circulating leptin levels and depressive symptoms, mild/moderate but not severe depression, and with self-reported depressive symptoms, especially in women, was recently identified." (PMID 33066277, 2020). "Furthermore, it is important to determine alterations in dopaminergic receptors in brain areas of mice exposed to LPS depression model, to better address the participation of these receptors in this inflammatory model as well as the effects of leptin administration in these receptors." (PMID 30949073, 2019). "In addition, the slowdown of the nocturnal increases in leptin among night eaters might lead to depression or depressive symptoms." (PMID 31805668, 2019). "In the multivariate model, the change in leptin levels over time was significantly associated with the total MFSI‐SF score (β = −0.15, P = 0.003) after adjusting for the tumour necrosis factor‐α (TNF‐α) level, anxiety, depression, insomnia, age, menopausal status and type of chemotherapy." (PMID 31016867, 2019). "Interestingly, while leptin is thought to be involved in synaptic plasticity in hippocampus, it also plays versatile roles on behaviors by affecting neural transduction such as anxiety and depression in diabetic rats." (PMID 30551684, 2018). "However, the relevance of leptin in depression vs. T2DM and CVD remains unclear due to the fact that divergent reports have associated depression with both hypo and hyperleptinemia." (PMID 29190710, 2017). "Although it is as yet unclear why there is a gender difference in circulating leptin levels in depression, our study may have uncovered a potential biological link between circulating leptin levels and depression, particularly in women, in the presence of abdominal obesity." (PMID 29176959, 2017). "In addition, leptin levels correlated negatively with several clinical fibromyalgia parameters, such as pain intensity, fatigue and anxiety, and with the quality of life scores, depression, sleep, and FIQ." (PMID 28226002, 2017). "Alternatively, there may be a gender difference in the relationship between leptin and depression." (PMID 25079305, 2014). "Thus, the role of leptin in patients with depression remains inconsistent." (PMID 25061971, 2014). "Also lower dosages of leptin could potentially ameliorate hyperactivity, depression, the metabolic profile, and reproductive function in acutely ill AN patients after weight regain." (PMID 24106499, 2013). "Moreover, growing evidence indicates that leptin is a pleiotropic hormone that exhibits diverse central actions including its ability to regulate hippocampal synaptic plasticity and to play a role in mood disorders such as depression." (PMID 22254146, 2012). "Thus, the increase in serum adiponectin levels suggests that its anti-inflammatory activity may counteract or offset the pro-inflammatory processes promoted by leptin, resistin, and other inflammatory immune mediators in pregnant individuals experiencing severe anxiety and depression." (PMID 40565847, 2025). "Research has also associated other pro-inflammatory biomarkers with mental health disorders and complement component 3 (C3), interleukin 6 (IL-6), leptin and white blood cell count (WBC) concentrations are reported to be higher in subjects with depression." (PMID 38560580, 2024). "We suggest further clinical investigations to determine the precise function of leptin and EGF in depression." (PMID 37399205, 2023). "Measuring the serum leptin and EGF levels alone cannot accurately represent the entire neuroinflammatory process of major depressive disorder." (PMID 37399205, 2023). "In this study, we investigated the involvement of EGF (a neurotrophic factor) and leptin (a pro-inflammatory cytokine) with MDD and depression severity." (PMID 37399205, 2023).
depression (continued). "Meta-analyses have not found evidence for differences in leptin concentrations between patients with major depressive disorder and healthy controls (HC), even if subgroup analyses implicated both high and low leptin concentrations in patients with major depressive disorder when compared to HC." (PMID 36037795, 2022). "However, other studies reported reduced plasma leptin in MDD patients with a normal BMI; this is consistent with rats or mice models of depression, which exhibited low circulating leptin levels." (PMID 35911226, 2022). "Therefore, it may be the case that an increase in central obesity contributes to an up-regulation of leptin and inflammatory factors which in turn leads to the onset depressive symptoms, whilst elevated IR seen with depression is purely a reflection of higher central adiposity." (PMID 29190710, 2017). "Some studies have shown that high baseline levels (or administration) of leptin and TNF-α lead to increased rates of de novo depression/onset depression-like symptoms." (PMID 29190710, 2017). "However, there is no report regarding association between leptin and depression in GC patients." (PMID 28316984, 2017). "Thus, we cannot rule out that lower leptin levels in association with increased Social Group Contact may be associated with depressive disorders or anxiety, similar to that described in response to social stress in humans and animal models." (PMID 29186207, 2017). "In addition, as recent studies have shown that insulin and leptin resistance in extra-hypothalamic brain regions may relate to neurological disorders, such as Alzheimer's disease and depression, it will be exiting to evaluate the participation of TLRs and high-fat feeding in these contexts." (PMID 19340313, 2009). "Future studies could further explore the clinical applications of biomarkers in CVD and depression by developing and validating biomarkers that can predict or diagnose CVD and depression (such as CRP and leptin)." (PMID 41601490, 2026). "Thereby, leptin fails to control feeding behaviour and mood, leading to key characteristics of atypical depression, such as hyperphagia." (PMID 41375608, 2025). "Some studies report a significant relationship between elevated leptin levels and depression, whereas others do not." (PMID 40507778, 2025). "Ultimately, leptin acts as a neurometabolic signal that links adiposity to BDNF-dependent and NMDAR-dependent synaptic plasticity, in addition to reward processing, mechanisms that are disrupted in depression." (PMID 41375608, 2025). "Research has demonstrated that leptin levels, as well as body mass index, are significantly higher in patients with moderate to severe depression compared to those with mild or no depression." (PMID 39335507, 2024). "In this study, we found an increase in plasma levels of leptin and OPG, and a decrease in levels of OC, OPN, SOST, PTH and FGF23 after six ketamine infusions in adults with depression, indicating that ketamine may mediate a beneficial effect on BMD." (PMID 38287453, 2024). "In addition, if any variation would be discovered, we sought to look into the relationship between changed serum leptin and EGF levels and the severity of depression." (PMID 37399205, 2023). "However, studies investigating the relationship of major depressive disorders (MDD) and leptin levels have yielded somewhat discrepant results." (PMID 38098007, 2023). "In conclusion, circulating leptin levels were not altered in patients with major depression compared to healthy controls." (PMID 38098007, 2023). "This shows that even though convincing evidence shows ghrelin, leptin and adiponectin to be involved in the pathophysiology of depression and depressive symptoms, this involvement does not necessarily manifest itself in altered serum levels." (PMID 35633817, 2022).